TRPM6 (transient receptor potential cation channel subfamily M member 6)
Diseases named in the same sentence as TRPM6 in open-access papers (continued):
Sharing a sentence is not in itself a finding about the gene and the disease.
cancer (15 papers, 2015 to 2026). A tumor composed of atypical neoplastic, often pleomorphic cells that invade other tissues. "In summary, through tumor phenotype experiments, this study provides preliminary evidence that TRPM6 deficiency promotes malignant progression in cancer cells." (PMID 41562086, 2025). "In pan-cancer, TRPM6 showed a robust positive association with resting memory CD4+ T cells (P < 0.01)." (PMID 41562086, 2025). "TRPM6 regulates cancers via neural pathways, associates with immune/tumor microenvironments, and has pan-cancer diagnostic value." (PMID 41562086, 2025). "Anti-epidermal growth factor receptor (EGFR) drugs used during cancer treatment cause TRPM6 upregulation and consequent hypomagnesemia in renal tubular epithelial NRK-52E cells." (PMID 33291725, 2020). "Transcriptome data from public databases were analyzed: differential expression of TRPM family genes in COAD and pan-cancer pathogenic associations of TRPM6 were assessed via the Wilcoxon test, with analyses of consensus molecular subtypes, clinical relevance, and survival also performed." (PMID 41562086, 2025). "In addition, TRPM6 also had the highest mutation frequency (15%) among TRP family genes in pan-cancer." (PMID 35493463, 2022). "However, the role of TRPM6, TRPM7, and TRPM6/7 induced risk of cancer in PPIH model requires further study." (PMID 36110961, 2022). "We were surprised to discover that TRPM6 played a role in upregulating genes in various types of cancers." (PMID 41562086, 2025). "Among the immune checkpoint inhibitors included in this study, the majority demonstrated positive correlations with TRPM6 across various cancer types." (PMID 41562086, 2025). "The present study identified significant cancer-type specificity in the correlations between TRPM6 and TMB/MSI, providing novel insights into the potential role of TRPM6 in genomic regulation and immune microenvironment modulation." (PMID 41562086, 2025). "TRPM4 was highly expressed in CHOL, and TRPM6 exhibited significantly lower expression in pan-cancer tissues, particularly in COAD and READ." (PMID 36830651, 2023). "TRPM6 has a tissue-specific expression and it is downregulated in several cancer types, while TRPM7 is ubiquitously expressed and mostly upregulated in different malignancies, where it plays a key role in promoting different cancer hallmarks." (PMID 35806388, 2022). "Comparison of structure-function activity between active (FL3, FL23) and inactive (FL2) flavaglines analogs revealed a positive correlation between cytostatic/cytotoxic properties of flavaglines in cancer cell lines and their action on TRPM6." (PMID 25774985, 2015). "Notably, pharmacological inhibition of TRPM6 and TRPM6/7 sharply reduced SP Mg2+ influx, intracellular Mg2+, cancer stemness, SP stability, and migration." (PMID 41596481, 2026). "TRPM6 has been studied less extensively in cancer than TRPM7." (PMID 40003994, 2025). "Furthermore, in pan-cancer, TRPM6 was negatively correlated with CD274, LAG3, PDCD1, and SIGLEC15, and showed significant differences (P < 0.01)." (PMID 41562086, 2025). "Interestingly, most investigations into TRPM4 and TRPM6 expression in cancer have reported alterations in their expression levels." (PMID 41562086, 2025). "This implies that TRPM6 might contribute to maintaining immune memory pools, potentially influencing long-term anti-tumor responses across diverse cancer types." (PMID 41562086, 2025). "Given that TRPM6 regulates neural synaptic pathways, it is plausible that TRPM6 may influence COAD development or aggressiveness through similar neuro-cancer cross-talk." (PMID 41562086, 2025). "Subsequent pan-cancer analyses indicated that TRPM6 may regulate highly relevant cancer types through modulation of neural synaptic pathways and displays high diagnostic value in COAD." (PMID 41562086, 2025).
cancer (continued). "hypothesizes that downregulation of TRPM6 contributes to severe hypomagnesemia in cancer patients treated with the monoclonal antibody targeting EGFR, cetuximab (CTX)." (PMID 36844925, 2022). "Additionally, to explore the pathways regulated by TRPM6, enrichment analysis indicated that TRPM6 may modulate highly relevant cancer types through the regulation of neural synaptic pathways." (PMID 41562086, 2025). "Moreover, the decreased expression of TRPM6 in cancer patients treated with EGFR targeted therapies (e.g., cetuximab) seems to positively contribute to the oncologic efficacy of these therapies, as decreased magnesium availability inhibits cell proliferation and slows down tumor growth." (PMID 35551258, 2022). "TRPM6 and TRPM7 also have emerging roles in cancer metastasis and oncogenesis." (PMID 40003994, 2025). "On the other hand, it could be speculated that, in cancer cells, autocrine signaling by EGF may potentiate the TRPM6-mediated magnesium influx or compete with CTX." (PMID 33114586, 2020). "Several genes with recurrent mutations were likely chance events, enhanced by their large size: DNAH11 (4516aa), TTN (34350aa), PIEZO1 (2521aa), TRPM6 (2022aa); none are thought to be involved in the pathogenesis of any form of cancer." (PMID 30256787, 2018).
tumor (10 papers, 2011 to 2025). "For example, TRPM6 is expressed in tumor-associated macrophages (TAMs) and modulates their phagocytic function and pro-inflammatory phenotype by participating in calcium signaling pathways." (PMID 41562086, 2025). "Subsequently, this study represents the first report to uncover the regulatory mechanism underlying TRPM6-mediated magnesium ion (Mg2+) tumor suppression, which operates through the neural pathway-immune microenvironment axis." (PMID 41562086, 2025). "As TRPM6 is a key regulatory molecule of Mg2+ channels, its deficiency might impair Mg2+ transport and its potential tumor-suppressive effects." (PMID 41562086, 2025). "Similarly, TRPM6 demonstrated intimate associations with both the immune and tumor microenvironment, suggesting its potential role as a regulator and a candidate biomarker for tumor immunobiology." (PMID 41562086, 2025). "Existing studies suggest that Mg2+ can regulate intracellular Mg2+ concentration through TRPM6, thereby affecting DNA repair enzyme activity or metabolic pathways—key processes that influence tumor cell survival and proliferation." (PMID 41562086, 2025). "TRPM6 exerts intricate and multifaceted effects in regulating the infiltration and functional status of pivotal immune cells within the tumor stroma." (PMID 41562086, 2025). "Within the validated mutations, somatic mutations in the TRPM6, HYDIN, ENTHD1, and NDUFB10 genes were found in two or more tumor samples in the replication stage." (PMID 26870154, 2015). "Notably, in cells subjected to both TRPM6 knockdown and high Mg2+ treatment, the tumor-suppressive effects mediated by Mg2+ were significantly attenuated." (PMID 41562086, 2025). "As the upstream initiating event, TRPM6 mediates Mg2+ influx into tumor and stromal cells—Mg2+, as a cofactor for multiple enzymes, first regulates neuro pathway-related genes by enhancing their transcriptional activity or stabilizing mRNA, thereby modulating neural synaptic pathways signaling." (PMID 41562086, 2025). "TRPM6 could play oncogenic/tumor suppressive roles through its ability to mediate Mg2+ homeostasis and its kinase functions." (PMID 36844925, 2022). "Thereby, dysfunction of the TRPM6 protein may affect the cation homeostasis leading to the tumor development." (PMID 26870154, 2015). "Notably, TRPM6 was downregulated in tumor samples of COAD (P < 0.05)." (PMID 41562086, 2025). "Such a phenotype implies TRPM6 may serve as a potential marker to identify tumors with latent immune responsiveness, providing a rationale for combining TRPM6 targeting with immunotherapies to enhance anti-tumor immunity." (PMID 41562086, 2025). "Specifically, TRPM1 and TRPM2 were upregulated in tumor tissues, whereas TRPM4, TRPM6, TRPM7, and TRPM8 were downregulated in the tumor group." (PMID 41562086, 2025). "First, the functional validation of TRPM6 and TRPM4 was restricted to two CRC cell lines (HCT116 and SW480), and in vivo animal models are needed to confirm their roles in tumor progression." (PMID 41562086, 2025). "Four consistent genes were differentially expressed in tumor tissues compared to normal tissues: two Ca2+-activated channels coding genes were induced (KCNN4, TRPM2) while KCNMA1 and TRPM6 were downregulated during the malignant transformation." (PMID 31010205, 2019). "Concurrently, RT-qPCR analysis revealed that the expression levels of tumor proliferation markers (MCM2 and Ki-67) and epithelial-mesenchymal transition (EMT)-related markers (CDH2, VIM, and FN1) were also significantly elevated following TRPM6 knockdown, consistent with the phenotype assay results." (PMID 41562086, 2025).
infection (2 papers, 2015 to 2025). The state of being infected such as from the introduction of a foreign agent such as serum, vaccine, antigenic substance or organism. "Additionally, genes involved in calcium signaling and ion channel regulation—PKD1, PKHD1, TRPC1, TRPM6, and TRPM7—highlight the importance of cellular homeostasis and signaling during infection." (PMID 41114509, 2025).
cardiovascular diseases (1 paper, 2021). "Our findings also suggest that a disease condition such as IHD could increase their expression, and this might indicate that TRPM7 as well as the TRPM6 are involved in the pathophysiology of cardiovascular diseases." (PMID 34326388, 2021).
metabolic disorders (1 paper, 2023). "TRPM6, a potential transient receptor channel, was previously reported to play a prominent role in regulating vertebrate embryonic development, hypomagnesemia, and metabolic disorders, and may be a promising drug target." (PMID 37650285, 2023).
TRPM6 also shares sentences with these, for which no sentence is quoted: Meningomyelocele (5 papers); Hypocalciuria (3); Hypokalemia (2); ischemic heart disease (2); lung adenocarcinoma (2); spina bifida (2); advanced heart failure (1); alcohol abuse (1); Alzheimer disease (1); amyotrophic lateral sclerosis (1); APRT deficiency (1); autosomal dominant polycystic kidney disease (1); calcinosis (1); channelopathies (1); colon (1); colon adenocarcinoma (1); epilepsy (1); Fanconi syndrome (1); glioblastoma multiforme (1); glioma (1); head and neck squamous cell carcinoma (1); hepatocellular carcinoma (1); hydronephrosis (1); Hyperglycemia (1); hypoparathyroidism (1); hypophosphatemic rickets (1); inflammation (1); kidney (1); Kyphosis (1); liver fibrosis (1).
A further 16 diseases each share a sentence with TRPM6 in 1 paper.